AGAP11 (ArfGAP with GTPase domain, ankyrin repeat and PH domain 11)
Description:
Putative GTPase-activating protein.
Synonyms: KIAA1975
Gene: Transcribed unprocessed pseudogene on chromosome 10 (87,001,636 to 87,009,905, forward strand). Ensembl gene ENSG00000261011.
Diseases named in the same sentence as AGAP11 in open-access papers:
AGAP11 is named in the same sentence as 5 diseases in open-access papers, as found by Europe PMC text mining. Sharing a sentence is not in itself a finding about the gene and the disease. The quoted sentences say what the papers report.
liver cancer (1 paper, 2023). An epithelial or non-epithelial malignant neoplasm that arises from the liver. "Although no experimental data pertaining to AGAP11 have been reported in the field of cancer, there is evidence to suggest that closely related genes, namely, LPL, MMP9, SGK1, TLR4, and FOS play certain roles in liver cancer through different mechanisms." (PMID 36726348, 2023). "Secondly, relevant experimental data demonstrating the relationship between the AGAP11 and FAM182B genes and the prognosis of HCC are lacking; however, the significantly related genes used in this study have been confirmed to be involved in the occurrence of liver cancer." (PMID 36726348, 2023).
oral cancer (1 paper, 2020). "However, the average expression level of AGAP11 in oral cancer samples obtained from TCGA database was low." (PMID 32571304, 2020).
cancer (3 papers, 2013 to 2023). A tumor composed of atypical neoplastic, often pleomorphic cells that invade other tissues. "While little prior evidence exists linking AGAP11 to cancer susceptibility, survival, or treatment response, some evidence exists for the role of C10orf116." (PMID 23555554, 2013). "To date, no literature has shown the link between AGAP11 and cancer survival." (PMID 33968126, 2021).
tumor (1 paper, 2023). "In light of our data, AGAP11 could be an NB tumor suppressor lncRNA at the 10q23.2 region, which needs to be checked with cellular functional studies." (PMID 37046696, 2023). "Six genes CCSER2, AGAP11, IFIT2, PAPSS2, PCGF5, and NUDT9P1 were observed to have potential NB tumor suppressor activity since their low expression was associated with poor survival even after correction for confounding by other prognostic factors (MYCN status, age at diagnosis, stage of disease)." (PMID 37046696, 2023).
AGAP11 also shares sentences with these, for which no sentence is quoted: ovarian carcinoma (1 paper).